TEX13B (testis expressed 13B)
Synonyms: TSGA5; TGC3B
Tractability: No criterion of Open Targets' tractability assessment is met for any kind of drug.
Gene: Protein-coding gene on chromosome X (107,980,864 to 107,982,370, reverse strand). Ensembl gene ENSG00000170925.
Gene Ontology:
Molecular function: protein binding
Homologues: Orthologues: chimpanzee TEX13B (99% identical), macaque TEX13B (79% identical), dog TEX13B (46% identical), rat Tex13a (38% identical), mouse Tex13a (38% identical), rat Tex13b (32% identical), mouse Tex13b (31% identical), Drosophila melanogaster CG14718 (12% identical). Paralogues in human: TEX13A (52% identical), TEX13C (25% identical), TEX13D (25% identical).
Diseases named in the same sentence as TEX13B in open-access papers:
TEX13B is named in the same sentence as 3 diseases in open-access papers, as found by Europe PMC text mining. Sharing a sentence is not in itself a finding about the gene and the disease. The quoted sentences say what the papers report.
gastric cancer (1 paper, 2021). A primary or metastatic malignant neoplasm involving the stomach. "The VSIG1 gene is expressed in the normal testis and stomach, as well as in esophageal, ovarian, and gastric cancers, the TEX13B that is expressed in the testis during spermatogonia." (PMID 34777475, 2021).
tumor (1 paper, 2014). "TCF7L1, TEX13B, and DSCAML1 mutations, which were detected during exome sequencing, were not confirmed in subsequent Sanger sequencing of the primary tumor or any metastatic specimens." (PMID 24406431, 2014).
TEX13B also shares sentences with these, for which no sentence is quoted: Allergy (1 paper).